FGF21 (fibroblast growth factor 21)
Diseases named in the same sentence as FGF21 in open-access papers (continued):
Sharing a sentence is not in itself a finding about the gene and the disease.
type 2 diabetes (continued). "The precise mechanism is not yet clear, even so, increased secretion of batokines after BAT activation and browning of sWAT, such as adiponectin and Fgf21, may also exert beneficial effects on treating type 2 diabetes and associated several metabolic comorbidities." (PMID 32190098, 2020). "FGF-21, known to regulate glucose and lipid metabolism, was previously reported to correlate positively with triglycerides in type 2 diabetes; a similar relationship with triglycerides was observed in our study for FGF-19 and FGF-22." (PMID 40943671, 2025). "HEC88473 is a bi-specific fusion protein of GLP-1/FGF21 that has already been clinically used to manage blood glucose control, weight loss, and NASH in patients with type 2 diabetes." (PMID 40636296, 2025). "Through Mendelian randomization we demonstrate potentially causal effects of FGF21 and HAVCR1 on risk for type 2 diabetes, of HPGDS on BMI, and of OXT on risk for lacunar stroke." (PMID 40225784, 2025). "For example, FGF21 analogs can significantly increase plasma lipocalin levels in obese and type 2 diabetic patients." (PMID 40881124, 2025). "Emerging clinical evidence demonstrates that elevated circulating FGF21 can be used as a biomarker of metabolic diseases such as metabolic dysfunction–associated steatohepatitis (MASH) and type 2 diabetes." (PMID 38889010, 2024). "FGF21 analogs have been studied in clinical trials for type 2 diabetes and NAFLD and have demonstrated generally good tolerability." (PMID 39144082, 2024). "Inhibitors of DDP4 have been developed and approved for the oral treatment of type 2 diabetes, and these drugs induce FGF21 expression and reduce angiotensin levels." (PMID 39511582, 2024). "In clinical studies, a higher plasma FGF21 concentration has been found in obese patients with metabolic disorders, impaired glucose tolerance, dyslipidemia, nonalcoholic liver disease, and type 2 diabetes." (PMID 39064306, 2024). "Consistent results were shown in human studies, which reported that administration of FGF21 analogs decreased body weight and increased insulin sensitivity in people with type 2 diabetes." (PMID 38178259, 2024). "In animal experiments and in clinical studies, it was found that the plasma FGF21 concentration is higher in obese subjects, as well as those with a metabolic syndrome and type 2 diabetes." (PMID 39064306, 2024). "For instance, in obese type 2 diabetic patients with peripheral neuropathy (BMI: 31.6 ± 3.9 kg/m2), 6 weeks of moderately intensive physical activity increased serum FGF21." (PMID 36837889, 2023). "Treatment of overweight/obese type 2 diabetic patients with the long-acting FGF21 analogue (PF-05231023) significantly reduced circulating triglyceride and low-density sterol levels and increased high-density lipoprotein and adiponectin levels." (PMID 37576954, 2023). "Analogues of the hepatokine fibroblast growth factor 21 (FGF21) are in clinical development for type 2 diabetes and nonalcoholic steatohepatitis (NASH) treatment." (PMID 36648330, 2023). "The fibroblast growth factor 21 (FGF21) has been identified as a promising therapeutic agent for type 2 diabetes and other metabolic diseases." (PMID 37047810, 2023). "A controlled trial found that FGF21 promotes glucose transport in the extensor digitorum longus muscle and soleus muscle of patients with type 2 diabetes to compensate for decreased insulin sensitivity." (PMID 38069273, 2023). "Liver fat content was increased in newly diagnosed overweight patients with type 2 diabetes combined with nonalcoholic fatty liver disease (NAFLD) compared to individuals in the control group, and was associated with high levels of FGF21." (PMID 37576954, 2023). "Our findings demonstrate that liver-derived FGF21 is involved in the GCGR antagonism-induced beta cell regeneration in a mouse model of type 2 diabetes." (PMID 36331598, 2023).
type 2 diabetes (continued). "In conclusion, our study demonstrates that GCGR mAb not only ameliorates hyperglycaemia but also increases functional beta cell mass in mouse models of type 2 diabetes, and that these effects are at least partly mediated via liver-derived FGF21." (PMID 36331598, 2023). "In type 2 diabetes, circulating FGF21 levels are biomarkers for diabetic retinopathy and severe diabetic retinopathy." (PMID 36943533, 2023). "ELP fusion with FGF-21 (fibroblast growth factor 21) is also involved in the treatment of type II diabetes by controlling blood glucose for 5 days." (PMID 36850121, 2023). "Consistently, higher FGF21 level is also significantly associated with the incidence of proteinuria and ESRD in patients with type 2 diabetes." (PMID 37009852, 2023). "Recently, AKR-001, an Fc-FGF21 analog, also showed beneficial effects on insulin sensitivity and lipoprotein profile in Type 2 diabetes patients." (PMID 35983184, 2022). "The FGF21 variant LY2405319 has been tested in patients with obesity and type 2 diabetes, with beneficial effects on lipid metabolism, body weight, fasting insulin and adiponectin levels, but no significant reduction in fasting glucose levels." (PMID 36500979, 2022). "In terms of associations with FGF21, sodium-glucose transport protein-2 (SGLT-2) inhibitor is being used for the treatment of type 2 diabetes, with the associated mechanisms involving inhibition of glucose absorption in renal tubules." (PMID 35877443, 2022). "To date, a variety of adipokines related to type 2 diabetes have been discovered and identified, including Adiponectin, Leptin, Visfatin, IL-6 and FGF21, etc." (PMID 35712241, 2022). "There is evidence existing to support that genetic variation in the FGF21 gene region is related to the renal function of type 2 diabetes patients and affects the eGFR of diabetic patients." (PMID 34675822, 2021). "Serum FGF21 has been confirmed as a biomarker for predicting rapid progression of CKD patients with type 2 diabetes through eGFR decline." (PMID 34675822, 2021). "Previous studies have shown that administration of recombinant FGF21 reduces the levels of blood glucose and lipids and improves insulin sensitivity in type 2 diabetic mice." (PMID 34773993, 2021). "In overweight patients with type 2 diabetes, the fibroblast growth factor 21 (FGF21) analog showed decreased plasma lipids, increased blood adiponectin levels, and significantly decreased body weight." (PMID 34768543, 2021). "Excessive serum levels of FGF21 were reported in atherosclerosis patients with ischemic heart disease as well as in non-alcoholic fatty liver disease, type 2 diabetes, and metabolic disorders." (PMID 34095143, 2021). "A study has found that the high serum FGF21 level is correlated with low urinary glucose excretion (UGE) in type 2 diabetes patients." (PMID 34675822, 2021). "LY2405319, another FGF21 analog, was found to improve lipid levels, lipoprotein profile, body weight, fasting insulin, and adiponectin levels in obese patients with type 2 diabetes in a randomized, placebo-controlled, double-blind clinical trial." (PMID 34513950, 2021). "Fibroblast growth factor 21 (FGF21) has been shown to suppress nephropathy in both type 1 and type 2 diabetes mice." (PMID 34773993, 2021). "FGF21 is produced in various tissues, especially in the liver, and improves lipid profiles in patients with type 2 diabetes." (PMID 34502311, 2021). "Further prospective studies in other populations are warranted to validate the predictive value of FGF21/adiponectin ratio in type 2 diabetes." (PMID 34321008, 2021). "FGF21 concentration is positively associated with carotid intima-media thickness and PWV in patients on haemodialysis and patients with type 2 diabetes." (PMID 32156043, 2020).
type 2 diabetes (continued). "It has been reported that FGF21 had therapeutic effects on glucose and lipid metabolism in mice and especially, long-acting FGF21 (PF-05231023) improved the levels of the circulating lipid profile in type 2 diabetic patients and in obese cynomolgus monkeys." (PMID 33086679, 2020). "That is consistent with a previous report of pemafibrate increasing FGF21 expression in type 2 diabetes with hypertriglyceridemia." (PMID 32872333, 2020). "FGF21 levels are also increased in type 2 diabetes and is positively correlated with BMI, insulin resistance, hyperglycemia, NAFLD, hyperlipidemia and hepatic triglycerides." (PMID 32372975, 2020). "In a recent clinical study (NCT02097277) of pegbelfermin (BMS-986036, polyethylene glycol-attached, PEGylated FGF21), however, little effect on Hb1Ac or body weight was observed in obese patients with type 2 diabetes." (PMID 32225108, 2020). "The requirement for supraphysiological doses of FGF21 to halt the pathogenesis of these diseases is consistent with FGF21 resistance in type 2 diabetes and CVDs." (PMID 32227589, 2020). "In humans with type 2 diabetes (T2D), chronic administration of FGF21 analogs lowers body weight and improves plasma lipid profiles." (PMID 31918921, 2020). "FGF21 reduces body weight and improves the lipid profile in patients with Type 2 diabetes, as well as in primate and rodent models of Type 2 diabetes." (PMID 32054022, 2020). "Systemic administration of FGF21 has favorable effects on glucose and lipid metabolism in mice and improves the level of blood lipids in type 2 diabetic patients." (PMID 31771164, 2019). "Further investigations with a larger sample size as well as functional studies are needed to elucidate how FGF21 is involved in renal function in patients with type 2 diabetes." (PMID 31205953, 2019). "Our group has proved that recombinant FGF21 protects against BBB leakage through Nrf2 upregulation in type 2 diabetes mice." (PMID 31101061, 2019). "In two recent clinical trials, long-acting FGF21 derivatives lowered body weight and insulin levels in obese subjects with type 2 diabetes." (PMID 31627352, 2019). "In several studies, metformin administration in type 2 diabetic patients led to an increase of serum fibroblast growth factor 21 (FGF21) concentrations; a hormone increased in muscle wasting and degeneration." (PMID 31480705, 2019). "Since FGF21 regulates important aspect of metabolism, it represents an attractive potential pharmaceutical target for treatment of obesity, type 2 diabetes, and dyslipidemia." (PMID 31627352, 2019). "When the carbohydrate/fat ratio was high (LP/HC), mice developed type 2 diabetes despite the robustly elevated hepatic FGF21 secretion and increased energy expenditure." (PMID 29550873, 2018). "High-fat-diet/streptozotocin-induced type 2 diabetes was established in both wild-type (WT) and FGF21-knockout (FGF21-KO) mice followed by treating with FGF21 for 4 months." (PMID 29445083, 2018). "Extensive clinical and animal data indicate that FGF21 is a promising first-line treatment drug for type 2 diabetes." (PMID 29949887, 2018). "Recent studies have reported that an elevated circulating FGF21 level predicts cardiovascular events and death in patients with type 2 diabetes and coronary artery disease, including early-stage CKD patients." (PMID 28582462, 2017). "Recent studies showed that the circulating FGF21 level predicts the rates of cardiovascular events and mortality in patients with type 2 diabetes and coronary artery disease." (PMID 28582462, 2017). "Therefore, in the present study, we investigated the change of FGF-21 and irisin levels in various skeletal muscles, and their association with muscle strength, following 8 weeks of resistance training, using Zucker diabetic fatty rats (type 2 diabetic animal models)." (PMID 29036766, 2017). "Fibroblast growth factor 21 (FGF21) is considered to be a promising therapeutic candidate for the treatment of type 2 diabetes." (PMID 28770320, 2017).
type 2 diabetes (continued). "As was reported in other studies, FGF21 was found to be significantly correlated with subclinical atherosclerosis and lower extremity atherosclerosis in type 2 diabetes patients." (PMID 28821258, 2017). "The sera from a normal glucose tolerance group (n = 68) and a prediabetes/type 2 diabetes group (n = 110) were collected; then, circulating levels of CTRP1, adiponectin, and FGF21 were determined via enzyme-linked immunosorbent assay in all sera." (PMID 27313611, 2016). "FGF-21 is a key regulator of metabolism and potential drug candidate for the treatment of type II diabetes and other metabolic disorders." (PMID 26962859, 2016). "The ability of FGF-21 to positively impact glucose and lipid homeostasis in the context of metabolic syndrome has led to investigation of FGF-21 as a therapeutic molecule for type 2 diabetes." (PMID 26962859, 2016). "Elevated serum FGF21 levels are also observed in patients with CHD and associate with both carotid atherosclerosis in women and carotid artery plaques in type 2 diabetes subjects." (PMID 26594197, 2015). "Serum FGF21 is elevated in newly diagnosed type 2 diabetes, and positively correlates with carotid and iliac lesions in patients with subclinical atherosclerosis, especially in women." (PMID 26047614, 2015). "In our study, we have shown that serum FGF21 is elevated in newly diagnosed type 2 diabetes, and positively correlates with carotid and iliac lesions in patients with subclinical atherosclerosis, especially in women." (PMID 26047614, 2015). "Multiple logistic regression analysis further showed that serum FGF21 was an independent impact factor for subclinical atherosclerosis in patients with type 2 diabetes." (PMID 26047614, 2015). "LY2405319 is the first FGF21 analog to enter human clinical trial, a phase I study was conducted in obese subjects with type 2 diabetes." (PMID 26594197, 2015). "Many different approaches have been pursued targeting FGF21 and its receptors to develop therapeutics for treating type 2 diabetes and other aspects of metabolic conditions." (PMID 26594197, 2015). "In summary, the results from the present study suggest that serum FGF21 concentrations are higher in patients with type 2 diabetes than in age-, BMI-, and sex-matched controls." (PMID 24895642, 2014). "According to the results of conditional logistic regression analysis, FGF21 is likely to be one of the major contributors to the pathogenesis of both type 2 diabetes and diabetic retinopathy." (PMID 24895642, 2014). "It seems likely that FGF21 levels are unchanged in different physiological states but increased with stress in individuals who are either overweight or have type 2 diabetes, or NAFLD." (PMID 24900988, 2014). "An elevated muscular expression of FGF-21 was found in patients with type 2 diabetes and insulin was identified as a stimulator of muscle-FGF-21 in two separate studies." (PMID 23533568, 2013). "Owing to the small sample size, we were not able to correct the values for confounding factors also known to increase FGF21 levels, such as type 2 diabetes or NAFLD." (PMID 23999826, 2013). "Recently, increased FGF-21 mRNA expression in muscle was found in patients with type 2 diabetes, but the role for FGF-21 in muscle is not well understood." (PMID 23533568, 2013). "Our result is in agreement with a previous study, in which FGF-21 mRNA was found to be increased in muscle from subjects with type 2 diabetes and the expression was increased by hyperinsulinemia." (PMID 23533568, 2013). "Here we describe an engineering strategy to generate a potent and efficacious Fc-fused FGF21 analog as a potential therapeutic agent to treat human type 2 diabetes." (PMID 23209571, 2012). "Fibroblast growth factor 21 (FGF21) is a promising drug candidate for the treatment of type 2 diabetes." (PMID 23209571, 2012).
type 2 diabetes (continued). "On the other hand, some human studies have shown that serum FGF21 levels are increased in both obese individuals and patients with type 2 diabetes, which suggest that hyperglycemia and/or hyperinsulinemia can regulate FGF21 gene expression in humans." (PMID 21829679, 2011). "Current research suggests that elevated serum FGF21 levels in patients with type 2 diabetes and GDM may result from the body’s compensatory mechanism." (PMID 39819596, 2025). "None of the patients or controls had type II diabetes or known liver disease, two conditions associated with higher circulating levels of FGF21." (PMID 40788112, 2025). "Moreover, serum level of FGF21 has been suggested as a potential biomarker of many metabolic syndromes, such as type 2 diabetes (T2D), nonalcoholic fatty liver, hyperlipidemia, and cardiovascular diseases." (PMID 40005931, 2025). "Notably, several FGF21 analogs and mimetics have progressed to early phases of clinical trials involving patients with obesity, type 2 diabetes mellitus, or MASH." (PMID 38889010, 2024). "We therefore aimed to determine first, whether type 2 diabetes was associated with changes in IDOL expression and the relationship with glycemia and FGF21." (PMID 37094639, 2023). "Several studies suggest that FGF21 could be an excellent molecule to treat type 2 diabetes and could also be involved in the metabolic enhancement induced by some antidiabetic drugs." (PMID 37760776, 2023). "Besides, FGF21 increased insulin content in primary islets in a rat model of type 2 diabetes and increased beta cell number in a mouse model of type 2 diabetes." (PMID 36331598, 2023). "Drugs that mimic FGF21 have already been developed for type 2 diabetes." (PMID 36648330, 2023). "Additionally, some papers indicate the potential role of FGF21 as an early predictor of type 2 diabetes development." (PMID 37869250, 2023). "Further research is needed to examine the application of FGF21 in the treatment of type 2 diabetes." (PMID 35877443, 2022). "Plasma FGF21 levels could be an independent predictor of metabolic syndrome and type 2 diabetes in Caucasian and Chinese subjects." (PMID 35163521, 2022). "However, the relationship between the FGF21-adiponectin pathway and type 2 diabetes in humans is unclear." (PMID 34321008, 2021). "Moreover, a meta-analysis found that FGF21 level in the plasma of type 2 diabetes patients significantly increased compared with the control group, which was affected by the variables of body mass index (BMI), total cholesterol and triglycerides." (PMID 34675822, 2021). "Studies showed that FGF21 reduces blood glucose and regulates blood lipids without causing hypoglycemia in obese or type 2 diabetes patients, and FGF21 increases insulin sensitivity and improves islet β cell secretion and proliferation." (PMID 33995273, 2021). "However, circulating FGF21 levels are increased, whereas adiponectin concentrations are reduced in subjects with type 2 diabetes, suggesting dysfunction of the FGF21-adiponectin pathway." (PMID 34321008, 2021). "PF-05231023, an FGF21 analog, was reported to have beneficial effects on body weight, lipoprotein profile, and adiponectin concentrations in overweight/obese subjects with type 2 diabetes." (PMID 34513950, 2021). "On the other hand, prospective cohort studies demonstrated that FGF21 resistance precedes the onset of metabolic syndrome and type 2 diabetes in humans, suggesting that higher plasma FGF21 levels are an independent predictor of metabolic syndrome and type 2 diabetes." (PMID 32978487, 2020). "The positive associations of FGF21 with arterial stiffness in male and female patients on haemodialysis and patients with type 2 diabetes, and in obese women, could also suggest the compensatory antioxidative effects of FGF21 on increasing arterial stiffness." (PMID 32156043, 2020).